DYNC1LI1 (dynein cytoplasmic 1 light intermediate chain 1)
Description:
Acts as one of several non-catalytic accessory components of the cytoplasmic dynein 1 complex that are thought to be involved in linking dynein to cargos and to adapter proteins that regulate dynein function. Cytoplasmic dynein 1 acts as a motor for the intracellular retrograde motility of vesicles and organelles along microtubules. May play a role in binding dynein to membranous organelles or chromosomes. Probably involved in the microtubule-dependent transport of pericentrin. Is required for progress through the spindle assembly checkpoint. The phosphorylated form appears to be involved in the selective removal of MAD1L1 and MAD1L2 but not BUB1B from kinetochores. Forms a functional Rab11/RAB11FIP3/dynein complex onto endosomal membrane that regulates the movement of peripheral sorting endosomes (SE) along microtubule tracks toward the microtubule organizing center/centrosome, generating the endosomal recycling compartment (ERC).
Synonyms: LIC1; DLC-A; DLIC-1; DNCLI1
Tractability: Antibody: its Gene Ontology location is reachable by antibodies, with high confidence. PROTAC: ubiquitination databases record sites on it; its protein half-life has been measured.
Gene: Protein-coding gene on chromosome 3 (32,525,974 to 32,570,900, reverse strand). Ensembl gene ENSG00000144635.
Subcellular location: Cytoplasm; Chromosome, centromere, kinetochore; Cytoplasm, cytoskeleton, spindle pole; Recycling endosome membrane
Subcellular location (Human Protein Atlas): Centrosome; Cytosol; Nucleoplasm; Plasma membrane
Pathways (Reactome):
Cell Cycle: Amplification of signal from unattached kinetochores via a MAD2 inhibitory signal; EML4 and NUDC in mitotic spindle formation; Mitotic Prometaphase; Resolution of Sister Chromatid Cohesion; Separation of Sister Chromatids
Immune System: MHC class II antigen presentation; Neutrophil degranulation
Vesicle-mediated transport: COPI-independent Golgi-to-ER retrograde traffic; COPI-mediated anterograde transport
Autophagy: Aggrephagy
Cellular responses to stimuli: HSP90 chaperone cycle for steroid hormone receptors (SHR) in the presence of ligand
Disease: HCMV Early Events
Signal Transduction: RHO GTPases Activate Formins
Gene Ontology:
Molecular function: dynein heavy chain binding; GDP binding; GTP binding; molecular adaptor activity; protein binding; protein-macromolecule adaptor activity; RNA binding
Biological process: endocytic recycling; microtubule-based movement; positive regulation of mitotic cell cycle spindle assembly checkpoint; regulation of vesicle-mediated transport; microtubule cytoskeleton organization; positive regulation of intracellular transport
Cellular component: centrosome; cytoplasmic dynein complex; endocytic vesicle membrane; kinetochore; membrane; recycling endosome membrane; spindle pole; cytosol; ficolin-1-rich granule membrane; male germ cell nucleus; microtubule; plasma membrane; secretory granule membrane; cytoplasm
Genetic constraint (gnomAD): Loss-of-function variants: 11 observed, 36.3 expected, observed/expected ratio (o/e) 0.3, 90% interval 0.19 to 0.5. The upper end of that interval is the gene's LOEUF score, 0.5, which puts it in group 2 of 6, group 1 being the genes least tolerant of losing a copy. Missense variants: 416 observed, 455.18 expected, observed/expected ratio (o/e) 0.91, 90% interval 0.84 to 0.99. Synonymous variants: 168 observed, 173.62 expected, observed/expected ratio (o/e) 0.97, 90% interval 0.85 to 1.1.
Homologues: Orthologues: chimpanzee DYNC1LI1 (100% identical), macaque DYNC1LI1 (99% identical), guinea pig DYNC1LI1 (97% identical), dog DYNC1LI1 (97% identical), pig DYNC1LI1 (97% identical), rat Dync1li1 (95% identical), mouse Dync1li1 (95% identical), rabbit DYNC1LI1 (87% identical), tropical clawed frog dync1li1 (79% identical), zebrafish dync1li1 (65% identical), Drosophila melanogaster Dlic (43% identical), Caenorhabditis elegans dli-1 (28% identical). Paralogues in human: DYNC1LI2 (62% identical).
Diseases named in the same sentence as DYNC1LI1 in open-access papers:
DYNC1LI1 is named in the same sentence as 18 diseases in open-access papers, as found by Europe PMC text mining. Sharing a sentence is not in itself a finding about the gene and the disease. The quoted sentences say what the papers report.
colorectal cancer (2 papers, 2021 to 2024). A primary or metastatic malignant neoplasm that affects the colon or rectum. "Dynein cell light intermediate chain 1 (DYNC1LI1) influences the sensitivity of colorectal cancer to radiation and chemotherapy and is linked to pancreatic ductal adenocarcinoma, hepatocellular carcinoma and prostate cancer." (PMID 38466053, 2024). "Although not previously reported in DIPG to our knowledge, altered expression of DYNC1LI1 has been described in other malignancies (colorectal cancer and breast cancer in adults), with potential impact on therapy sensitivity." (PMID 33431066, 2021).
Atrophy (1 paper, 2022). Any weakening or degeneration, especially through lack of use. "Here we confirm that Dync1li1 KO mice have retinal defects and photoreceptor degradation demonstrated by atrophy at various levels of the retina." (PMID 36456625, 2022).
autism (1 paper, 2025). Persistent deficits in social interaction and communication and interaction as well as a markedly restricted repertoire of activity and interest as well as repetitive patterns of behavior. "Interestingly, four related proteins, DYNC1I1, DYNC1LI1, DYNC1LI2 and DYNLRB1 were also reduced significantly in cerebellar vermis of children with autism." (PMID 40779003, 2025).
ciliopathies (1 paper, 2022). "Five of these genes predicted to have ciliary interaction (Abi2, Wdr62, Ap4e1, Dync1li1, and Prkab1) had abnormal morphological features detected by imaging that are consistent with the spectrum of phenotypes observed in ciliopathies." (PMID 36456625, 2022). "Histological and morphological evidence of phenotypes found in ciliopathies in knockout mouse lines are presented as examples (genes Abi2, Wdr62, Ap4e1, Dync1li1, and Prkab1)." (PMID 36456625, 2022).
microphthalmia (1 paper, 2023). Congenital or developmental anomaly in which the eyeballs are abnormally small. "A similar search of DR17 using the term microphthalmia resulted in 22 genes significant for the small eyes phenotype: Aldh1a3, Aff4, Bmp4, Cdk4, Cox6b1, Cxcr4, Dync1li1, Eef1d, Fgd1, Gne, Grh12, Mab21l2, Maf, Med13l, Mllt10, Mthfd2, Pex6, Phgdh, Ssr1, Stim1, Tdo2, and Vps26c." (PMID 36737727, 2023).
tumor (2 papers, 2020 to 2024). "In tumor tissues, CCNB2, DYNC1LI1, SPC25 and KIF18A expressions were mainly detected in the cytoplasm, and KIF11 expression was detected mainly in the cytoplasm and nucleus." (PMID 33111935, 2020).
DYNC1LI1 also shares sentences with these, for which no sentence is quoted: hepatocellular carcinoma (2 papers); Alzheimer disease (1); amyotrophic lateral sclerosis (1); Anxiety (1); breast carcinoma (1); colon cancer (1); hearing loss (1); Huntington disease (1); motor neuron diseases (1); pancreatic ductal adenocarcinoma (1); prostate carcinoma (1); Septo-optic dysplasia (1).